LRRC8A (leucine rich repeat containing 8 VRAC subunit A)
Description:
Essential component of the volume-regulated anion channel (VRAC, also named VSOAC channel), an anion channel required to maintain a constant cell volume in response to extracellular or intracellular osmotic changes. The VRAC channel conducts iodide better than chloride and can also conduct organic osmolytes like taurine. Mediates efflux of amino acids, such as aspartate and glutamate, in response to osmotic stress. LRRC8A and LRRC8D are required for the uptake of the drug cisplatin. In complex with LRRC8C or LRRC8E, acts as a transporter of immunoreactive cyclic dinucleotide GMP-AMP (2'-3'-cGAMP), an immune messenger produced in response to DNA virus in the cytosol: mediates both import and export of 2'-3'-cGAMP, thereby promoting transfer of 2'-3'-cGAMP to bystander cells. In contrast, complexes containing LRRC8D inhibit transport of 2'-3'-cGAMP. Required for in vivo channel activity, together with at least one other family member (LRRC8B, LRRC8C, LRRC8D or LRRC8E); channel characteristics depend on the precise subunit composition. Can form functional channels by itself (in vitro). Involved in B-cell development: required for the pro-B cell to pre-B cell transition. Also required for T-cell development (By similarity). Required for myoblast differentiation: VRAC activity promotes membrane hyperpolarization and regulates insulin-stimulated glucose metabolism and oxygen consumption (By similarity). Also acts as a regulator of glucose-sensing in pancreatic beta cells: VRAC currents, generated in response to hypotonicity- or glucose-induced beta cell swelling, depolarize cells, thereby causing electrical excitation, leading to increase glucose sensitivity and insulin secretion. Also plays a role in lysosome homeostasis by forming functional lysosomal VRAC channels in response to low cytoplasmic ionic strength condition: lysosomal VRAC channels are necessary for the formation of large lysosome-derived vacuoles, which store and then expel excess water to maintain cytosolic water homeostasis. Acts as a key factor in NLRP3 inflammasome activation by modulating itaconate efflux and mitochondria function.
Synonyms: HsLRRC8A; KIAA1437; LRRC8; SWELL1; FLJ10337; AGM5
Tractability: Small molecule: a structure with a bound ligand is known. Antibody: UniProt places it where antibodies can reach, with high confidence; its Gene Ontology location is reachable by antibodies, with high confidence; UniProt predicts a signal peptide or a membrane-spanning region. PROTAC: ubiquitination databases record sites on it; its protein half-life has been measured.
Gene: Protein-coding gene on chromosome 9 (128,882,133 to 128,918,042, forward strand). Ensembl gene ENSG00000136802.
Subcellular location: Cell membrane; Lysosome membrane
Pathways (Reactome):
Transport of small molecules: Miscellaneous transport and binding events
Gene Ontology:
Molecular function: cyclic-GMP-AMP transmembrane transporter activity; identical protein binding; monoatomic anion channel activity; protein binding; volume-sensitive anion channel activity
Biological process: cell volume homeostasis; chloride transmembrane transport; cyclic-GMP-AMP transmembrane import across plasma membrane; monoatomic anion transmembrane transport; monoatomic anion transport; protein hexamerization; response to osmotic stress; aspartate transmembrane transport; intracellular glucose homeostasis; positive regulation of insulin secretion; positive regulation of myoblast differentiation; pre-B cell differentiation; spermatogenesis; taurine transmembrane transport
Cellular component: cell surface; lysosomal membrane; membrane; monoatomic ion channel complex; plasma membrane; cytoplasm
Genetic constraint (gnomAD): Loss-of-function variants: 24 observed, 54.93 expected, observed/expected ratio (o/e) 0.44, 90% interval 0.31 to 0.61. The upper end of that interval is the gene's LOEUF score, 0.61, which puts it in group 2 of 6, group 1 being the genes least tolerant of losing a copy. Missense variants: 677 observed, 1,142.8 expected, observed/expected ratio (o/e) 0.59, 90% interval 0.56 to 0.63. Synonymous variants: 492 observed, 517.08 expected, observed/expected ratio (o/e) 0.95, 90% interval 0.88 to 1.02.
Gene-disease validity (ClinGen):
ClinGen rates the evidence that LRRC8A causes each of these diseases.
agammaglobulinemia (autosomal dominant): Limited. A decreased level of serum immunoglobulins.
Homologues: Orthologues: chimpanzee LRRC8A (100% identical), macaque LRRC8A (100% identical), mouse Lrrc8a (99% identical), dog LRRC8A (99% identical), guinea pig LRRC8A (99% identical), pig LRRC8A (99% identical), rat Lrrc8a (99% identical), tropical clawed frog lrrc8a (90% identical), rabbit LRRC8A (89% identical), zebrafish lrrc8aa (86% identical), zebrafish lrrc8ab (85% identical). Paralogues in human: LRRC8B (58% identical), LRRC8C (57% identical), LRRC8D (55% identical), LRRC8E (53% identical), SCRIB (16% identical), PHLPP2 (16% identical), PHLPP1 (15% identical), ERBIN (15% identical), LRRC1 (15% identical), LRRD1 (15% identical), LRRC7 (15% identical), LRRIQ4 (15% identical), and 19 more.
Diseases named in the same sentence as LRRC8A in open-access papers:
LRRC8A is named in the same sentence as 91 diseases in open-access papers, as found by Europe PMC text mining. Sharing a sentence is not in itself a finding about the gene and the disease. The quoted sentences say what the papers report.
Insulin resistance (10 papers, 2018 to 2026). Increased resistance towards insulin, that is, diminished effectiveness of insulin in reducing blood glucose levels. "In vivo, skeletal muscle-targeted Lrrc8a KO mice have smaller skeletal muscle cells, impaired muscle endurance, and force generation, and are predisposed to adiposity, glucose intolerance and insulin resistance." (PMID 32930093, 2020). "Thus, adipose tissue-specific knockout of LRRC8A (Adipo KO) under obese conditions could exacerbate insulin resistance and impair glucose uptake, potentially escalating liver disease from steatosis to HCC." (PMID 41439137, 2026). "Extending these investigations to skeletal muscle, characterizing the involvement of LRRC8A in insulin resistance, including its interactions with glucose transporters and insulin signaling components, may uncover previously unrecognized mechanisms underlying systemic metabolic dysfunction." (PMID 41439137, 2026). "Our results suggest that reductions in LRRC8A signaling may contribute to impaired vascular function observed in humans in response to insulin and/or shear stress in the setting of obesity and insulin resistance." (PMID 33629656, 2021). "The impaired exercise capacity observed in skeletal muscle Lrrc8a KO mice are consistent with some level of insulin resistance, as in db/db mice and in humans, and may be due to impaired skeletal muscle glycolysis and oxygen consumption in LRRC8A-depleted skeletal muscle." (PMID 32930093, 2020). "However, overnutrition-induced obesity, and the associated impairments in adipose and hepatic glucose disposal may uncover glucose intolerance and insulin resistance in skeletal muscle-targeted Lrrc8a KO mice." (PMID 32930093, 2020).
breast cancer (9 papers, 2022 to 2026). A primary or metastatic malignant neoplasm involving the breast. "The results showed that IGLL1, SLAMF7, SLAMF1, CD48, and LRRC8A were closely associated with immune infiltration in breast cancer (p < 0.05)." (PMID 38388382, 2024). "Lower expression of the LRRC8A gene is associated with reduced sensitivity of breast cancer patients to chemotherapy drugs such as BX-912, AR-42, AT-7519, BHG712, CAL-101, and CAY10603." (PMID 38388382, 2024). "In the nude mouse xenograft model, LRRC8A knockdown suppressed the tumorigenesis of subcutaneously implanted breast cancer cells." (PMID 39882260, 2024). "We evaluated the correlation between the expression of IGLL1, SLAMF7, SLAMF1, CD48, and LRRC8A and the immune infiltration profile in breast cancer using data downloaded from TCGA." (PMID 38388382, 2024). "Further research is needed to investigate these results, and the results of the drug sensitivity analysis indicated that IGLL1, SLAMF7, SLAMF1, CD48, and LRRC8A might decrease sensitivity to specific chemotherapy drugs, further affecting the treatment efficacy for breast cancer." (PMID 38388382, 2024). "In three different types of breast cancer cells, differential expression was also observed in genes including HERV-K_1q23.3, CD48, SLAMF1, SLAMF7, HERV-K_22q11.23, IGLL1, HERV-K_9q34.11, and LRRC8A." (PMID 38388382, 2024). "A total of 88 candidate genes related to breast cancer prognosis were screened, of which CD48, SLAMF7, SLAMF1, IGLL1, IGHA1, and LRRC8A were key genes." (PMID 38388382, 2024). "Collectively, these findings suggest that LRRC8A inhibition may represent a therapeutic strategy to overcome chemoresistance by repressing MRP3 and/or CYP3A4 expression in breast cancer stem cells." (PMID 41898509, 2026). "Comparing the gene expression between normal breast epithelial cells and four types of breast cancer cells, it was found that all four different types of breast cancer cells exhibited differential expression of theHERV-K_1q23.3, SLAMF1, HERV-K_22q11.23, IGLL1, HERV-K_9q34.11 and LRRC8A." (PMID 38388382, 2024). "Additionally, the correlation between LRRC8A and CD8+ T-cell infiltration in various tumors, including lung cancer, breast cancer, cholangiocarcinoma, and 14 other tumor types, indicated that increased LRRC8A expression corresponded to higher levels of CD8+T cell infiltration in tumors." (PMID 39113714, 2024).
colon carcinoma (8 papers, 2022 to 2024). "Our team noticed that LRRC8A was an essential component of the volume-regulated ion channel, associated with poor prognoses in colon cancer patients by enhancing cancer cell proliferation and metastasis." (PMID 39678513, 2024). "Recently, it has been revealed that LRRC8A is one of the components of the exosomes released from colon cancer HCT116 cells." (PMID 38909013, 2024). "The expression of LRRC8A is elevated in the tissues of colorectal cancer patients, which correlates with a shortened survival time, and the knockdown of LRRC8A in colon cancer cells inhibits tumorigenesis in a xenograft model." (PMID 39882260, 2024). "In vivo studies in nude mouse models have also shown that LRRC8A downregulation suppressed the proliferation of colon carcinoma, hepatocellular carcinoma, and cervical cancer." (PMID 37538172, 2023). "Moreover, we re-evaluated the impact of LRRC8A on cellular proliferation and migration in colon cancer via HCT116 LRRC8A-KO cells, which is a current topic of debate in the literature." (PMID 38909013, 2024). "Some findings suggest that LRRC8A could serve as a novel biomarker for predicting the survival of colon cancer patients and that is a central mediator in mediating multiple signaling pathways to promote metastasis and targeting LRRC8A." (PMID 38909013, 2024). "Next, we observed that the LRRC8A expression in R-Oxa cells was significantly higher than that in native HCT116 cells, suggesting that LRRC8A may be an important factor in the acquisition of oxaliplatin resistance for colon cancer cells." (PMID 37313175, 2023). "LRRC8A promotes the initial development of oxaliplatin resistance in colon cancer cells." (PMID 37313175, 2023). "LRRC8A may be an intriguing potential target to interfere with the acquisition of oxaliplatin resistance for colon cancer cells in chemotherapy." (PMID 37313175, 2023). "Taken together, the maintenance of strong LRRC8A expression may be conducted by the drug stimulation, suggesting that LRRC8A may be an important factor in the acquisition of oxaliplatin resistance for colon cancer cells." (PMID 37313175, 2023). "In contrast, another study found that LRRC8A knockdown or gene knockout did not affect cell proliferation and migration in several cultured cell types, including myoblasts, colon cancer cells, and glioblastoma cells." (PMID 39882260, 2024). "Importantly, LRRC8A self- regulated its transcription via NF-κB1 and NF-κB2 pathways and the upregulation of NIK/NF-κB2/LRRC8A transcriptional axis was unfavorable for colon cancer patients." (PMID 38909013, 2024). "LRRC8A proteins were elevated during the chronic exposure to oxaliplatin, but it's not yet distinguished if the changed LRRC8A was an accompanied or indispensable event in the process of acquiring resistance to oxaliplatin in colon cancer cells." (PMID 37313175, 2023). "In conclusion, LRRC8A is involved in the acquisition of oxaliplatin resistance rather than the maintenance in colon cancer cells." (PMID 37313175, 2023). "While, LRRC8A, a main regulatory subunit of VRAC (volume-regulated anion channel), was found to be upregulated in colon cancer patients and might contribute to metastasis." (PMID 35552415, 2022). "Although the present study demonstrates that LRRC8A could promote the development of oxaliplatin resistance, it is still not clear that the mechanisms of LRRC8A assisting colon cancer cells to acquire drug resistance." (PMID 37313175, 2023). "The role of LRRC8A in oxaliplatin resistance in colon cancer was still not elucidated clearly." (PMID 37313175, 2023). "In our study, overexpression or knockdown of LRRC8A expression could alter the oxaliplatin resistance in native HCT116 cells, which suggest that LRRC8A contribute to the obtainment of oxaliplatin resistance in colon cancer cells." (PMID 37313175, 2023).
type 2 diabetes (8 papers, 2021 to 2026). "Endothelium-specific Lrrc8a KO mice exhibit exacerbated impairments retinal microvascular disease in the setting of type 2 diabetes." (PMID 33629656, 2021). "Delineating the signaling cascades through which LRRC8A modulates insulin secretion and β-cell viability could reveal novel targets for early intervention in type 2 diabetes pathogenesis." (PMID 41439137, 2026). "However, a recent study found that low-dose, long-term DCPIB administration improved systemic metabolism in type 2 diabetes via upregulation of LRRC8A in adipocytes." (PMID 36211567, 2022). "Endothelium-restricted Lrrc8a KO mice develop hypertension in response to chronic angiotensin-II infusion and exhibit impaired retinal blood flow with both diffuse and focal blood vessel narrowing in the setting of type 2 diabetes (T2D)." (PMID 33629656, 2021).
agammaglobulinemia (7 papers, 2020 to 2025). "Truncation of the C-terminus of LRRC8A as in patients with agammaglobulinemia caused cytoplasmic retention of all LRRC8 subunits, suggesting that the LRRD of LRRC8A is essential to the trafficking of this subunit, and therefore the remaining subunits, to the plasma membrane." (PMID 36035259, 2022). "Agammaglobulinemia with other inherited pattern were also concluded: AR agammaglobulinemia was associated with mutations in several other genes such as IGHM, IGLL1, CD79A, CD79B, BLNK, PIK3R1, and TCF3 genes; AD-related agammaglobulinemia was also found with LRRC8A and TCF3 gene mutations." (PMID 36140582, 2022). "SWELL1 or LRRC8a (leucine-rich repeat-containing protein 8a) encodes a transmembrane protein first described in 2003 as the site of a balanced translocation in an immunodeficient child with agammaglobulinemia and absent B-cells." (PMID 35145074, 2022). "The truncation of the LRRC8A C-terminus in the case of agammaglobulinemia leads to cytoplasmic retention of the subunit, suggesting that the LRR domain of LRRC8A facilitates subunit trafficking." (PMID 36035259, 2022). "Lrrc8a (leucine-rich repeat-containing protein 8A, also known as SWELL1) encodes a transmembrane protein first described as the site of a balanced translocation in an immunodeficient child with agammaglobulinemia and absent B-cells." (PMID 33629656, 2021). "Interestingly, LRRC8A was first found in a human patient with congenital agammaglobulinemia due to the lack of peripheral B cells, whereas a later study in mice also indicates that the LRRC8A participates in the homeostasis of lymphocytes." (PMID 31941702, 2020).
hepatocellular carcinoma (7 papers, 2020 to 2026). A malignant tumor that arises from hepatocytes. "For example, LRRC8A is highly expressed in hepatocellular carcinoma tissues, which inhibits apoptosis and strengthens cell proliferation and migration while promoting apoptosis in glioblastoma, ovarian, and alveolar carcinoma cells." (PMID 38018865, 2023). "This study indicates that targeting the JNK pathway or disrupting LRRC8A channel function may prevent hepatocellular carcinoma metastasis." (PMID 41439137, 2026). "In hepatocellular carcinoma, disrupting the LRRC8A-JNK axis could prevent metastasis." (PMID 41439137, 2026). "In hepatocellular carcinoma (HCC), LRRC8A activates the JNK MAPK cascade, leading to the phosphorylation and activation of the c-Jun transcription factor." (PMID 41439137, 2026).
gastric cancer (6 papers, 2022 to 2026). A primary or metastatic malignant neoplasm involving the stomach. "In gastric cancer, LRRC8A maintains intracellular chloride concentrations to support cancer cell survival under osmotic stress conditions." (PMID 41439137, 2026). "In light of these findings, targeting LRRC8A can simultaneously address metabolic adaptation and apoptosis resistance issues in gastric cancer." (PMID 41439137, 2026). "First, ICl,swell was not affected by shRNA-mediated knockdown of LRRC8A but, in contrast, was largely abolished by double knockout of TTYH1 and TTYH2 in gastric cancer SNU-601 cells." (PMID 38238667, 2024).
glioblastoma (6 papers, 2019 to 2024). The most malignant astrocytic tumor (WHO grade IV). "The siRNA-mediated knockdown of the obligate VRAC subunit LRRC8A was reported to limit the proliferation of glioblastoma cells and reduce the migration of human colon cancer HCT116 cells." (PMID 31151189, 2019). "Together, these results from pharmacological VRAC inhibition and LRRC8A knockdown suggest that VRAC is dispensable for glioblastoma cell proliferation and migration in the wound healing assay." (PMID 31151189, 2019). "Using this approach, siRNA-mediated downregulation of the essential VRAC subunit LRRC8A reduced proliferation of primary glioblastoma and U251 GBM cells, and knockdown of LRRC8A in the colorectal cancer cell line HCT116 was shown to impair cell migration in a wound healing assay." (PMID 31151189, 2019).